MCAM (melanoma cell adhesion molecule)
Diseases named in the same sentence as MCAM in open-access papers (continued):
Sharing a sentence is not in itself a finding about the gene and the disease.
hepatocellular carcinoma (20 papers, 2009 to 2025). A malignant tumor that arises from hepatocytes. "ALCAM and MCAM in combination seem to be promising candidates as diagnostic markers for hepatocellular carcinoma and their crosstalk has intensively been investigated in a hepatocellular carcinoma cell culture model, the Bel-7402 cells." (PMID 26703751, 2015). "Very recently, MCAM was also shown to regulate the stemness and chemoresistance of hepatocellular carcinoma through the activation of NFκB, resulting in an increased level of JAG2 and activation of the NOTCH pathway." (PMID 41388158, 2025). "CD146 was originally described as a melanoma cell adhesion molecule and is overexpressed in a range of solid tumors, including breast, prostate, and hepatocellular carcinoma." (PMID 40564089, 2025). "ST6GAL1 inhibits metastasis of hepatocellular carcinoma via modulating the sialylation of MCAM on the cell surface." (PMID 38274327, 2024). "Nevertheless, the results showing a tightly regulated expression of MCAM by ALCAM and the ubiquitination of MCAM provides novel and highly interesting insights into the cellular regulation of MCAM and hence into hepatocellular carcinoma and potential future therapeutic approaches." (PMID 26703751, 2015).
colorectal cancer (19 papers, 2012 to 2025). A primary or metastatic malignant neoplasm that affects the colon or rectum. "Similarly, a recent study reported that the melanoma cell adhesion molecule+ (MCAM+) CAFs induced by TGF-β in colorectal cancer patients were associated with poor prognosis." (PMID 36185262, 2022). "We also investigated the potential clinical-pathological relevance of NOX1, ADAM17, and MCAM expression in colorectal cancer." (PMID 38137406, 2023). "These links to cancer include recent studies which found that LAMA4 and MCAM (melanoma cell adhesion molecule) are highly enriched in tumor blood vessels in renal cell carcinoma and colorectal carcinoma." (PMID 32571313, 2020). "Furthermore, AIM2 played an protumor role in colorectal tumors because overexpression of AIM2 in colorectal cancer cells induced the expression of invasion‐associated genes such as VIM and MCAM." (PMID 35070978, 2021). "Correspondingly, in colorectal cancer, especially in the angiogenic CMS4 subtype, anti-MCAM antibodies inhibited tumor growth and angiogenesis by disrupting vascular signaling." (PMID 41388158, 2025). "Especially, the expression of MCAM, NOX1, and ADAM17 was more prominent in the angiogenic, colorectal cancer-consensus molecular subtype 4 where high MCAM expression correlated with angiogenic and lymphangiogenic markers." (PMID 38137406, 2023).
metastatic melanoma (19 papers, 2010 to 2025). A melanoma that has spread from its primary site to another anatomic site. "MCAM seems to be associated preferably to some tumors such as primary epidermoid carcinoma, colon cancer, primary and metastatic malignant melanoma, and metastatic lung cancer." (PMID 40332096, 2025). "Cluster of differentiation 146 (CD146) also named melanoma cell associated molecule (MCAM)/Mucin 18 (MUC18)/S-Endo 1 was first discovered in metastatic melanoma and its expression was rapidly associated to a bad prognosis." (PMID 31548532, 2017). "Loss of AP-2α in metastatic melanoma is directly linked to overexpression of melanoma cell adhesion molecule MCAM/MUC18, protease-activated receptor-1 (PAR-1), matrix metalloproteinase-2 (MMP-2), and loss of tyrosine-kinase receptor c-KIT." (PMID 20805990, 2010). "Melanoma cell adhesion molecule (MCAM), also named cluster of differentiation 146 (CD146), is an integral membrane glycoprotein belonging to the immunoglobulin (Ig) superfamily that was originally discovered in metastatic melanoma and to be associated with poor prognosis." (PMID 35790583, 2022). "Data from human studies also suggest that MCAM expression may be linked to the development of metastatic melanoma lesions." (PMID 24069584, 2013). "In summary, these results show that MCAM is abundantly expressed in both primary and metastatic melanomas." (PMID 39945026, 2025). "In conclusion, our results suggest that circ_0079593 can promote the migration of metastatic melanoma cells, increasing aggressiveness, through the regulation of the miR-516b-5p/MCAM and miR-516b-5p/CHAF1B axes." (PMID 39766913, 2024). "On the other hand, MCAM/MUC18, which has been shown to be upregulated in metastatic melanoma cell lines, was found to be significantly downregulated by 90% in both cell lines after CREB silencing." (PMID 20805990, 2010). "In our work, we observed a frequent expression of MCAM in most primary and metastatic melanomas." (PMID 39945026, 2025). "MUC18, also known as MCAM (melanoma cell adhesion molecule), CD146 (cluster of differentiation 146), or METCAM/MelCAM (metastatic melanoma CAM), is expressed on the surface of metastatic melanoma and other cancer cells." (PMID 33278894, 2020). "Melanoma cell adhesion molecule (MCAM) is a cell-surface adhesion molecule expressed by melanocytes in over 70% of metastatic melanoma cells, not being expressed in normal melanocytes in vivo." (PMID 32117980, 2020). "We confirmed that MCAM and CHAF1B were overexpressed compared to the healthy melanocyte cell line (NHEM) in both the commercial cutaneous melanoma cell line (A375) and short-term cutaneous and nodal metastatic melanoma cell lines (LM-36 and LM-16, respectively)." (PMID 39766913, 2024).
lung carcinoma (16 papers, 2015 to 2026). "MUC18, also known as MCAM/CD146, is a ubiquitous marker in various tumors, including lung cancer, where it has been implicated in tumor aggressiveness, angiogenesis, and poor prognosis." (PMID 40655139, 2025). "MCAM is thought to increase endothelial adherence of T cells to traffic to sites of inflammation and a higher percentage of CD146+ Treg in the blood of lung cancer patients compared to healthy controls has been reported." (PMID 37232845, 2023). "Melanoma cell adhesion molecule (MCAM), a cell surface receptor, was identified as being significantly up-regulated in chemoresistant lung cancer cells and patient-derived xenografts." (PMID 32708822, 2020). "Furthermore, MCAM which is up-regulated in lung cancer, is expressed in basal bronchial epithelial cells." (PMID 25944280, 2015).
glioblastoma (15 papers, 2014 to 2026). The most malignant astrocytic tumor (WHO grade IV). "These include Annexin A6 (ANXA6) and CD146/Melanoma cell adhesion molecule (MCAM), which were reported to promote radioresistance in nasopharyngeal carcinoma and glioblastoma multiforme, respectively." (PMID 40497995, 2025). "Pericytes and macrophages recognized by MCAM/CD163 gene pair expression have been identified as a potential prognostic immune signature co-expressed in glioblastoma (GBM) samples." (PMID 39086395, 2024). "This includes expression of PDGFR‐β/CD140b, MCAM/CD146, Thy‐1/CD90, fibronectin and several collagen genes, all of which have emerged as reliable markers of human pericytes in normal brain and glioblastoma." (PMID 33082953, 2020). "Moreover, our present findings further indicate that MCAM and LGALS1 also appear to constitute promising candidate molecules to deliver biopharmaceuticals from the blood across the BBB to glioblastomas." (PMID 32585920, 2020). "The final cell type common to all three specimens was characterised by expression of PDGFRB (PDGFRβ/CD140b), MCAM (CD146), THY1 (CD90), FN (fibronectin) and type IV collagen genes, markers typical of mature pericytes, including those in normal human brain and glioblastoma." (PMID 33082953, 2020).
gastric cancer (12 papers, 2012 to 2025). A primary or metastatic malignant neoplasm involving the stomach. "Furthermore, MCAM has been shown to correlate with metastasis in both colorectal and gastric cancers and was recognized as a significant prognostic factor." (PMID 41388158, 2025).
glioma (12 papers, 2016 to 2025). A benign or malignant brain and spinal cord tumor that arises from glial cells (astrocytes, oligodendrocytes, ependymal cells). "Meanwhile, MUC18, also known as CD146 and MCAM, has benefitted from significant literature interest, as it has been associated with glioma based on publications that have been in the public domain for a longer period." (PMID 39767713, 2024). "MCAM is overexpressed in high-grade gliomas, and the majority of glioma stem cells expressing CD133 are also MCAM-positive." (PMID 32585920, 2020). "In order to explore whether this contradiction exists in gliomas, we compared the expression levels of vascular stability-related markers (ANGPT1, ANGPT2, JAM2, MCAM, PDGFRB, and VE-Cadherin) in the high- and low-score glioma groups in the TCGA, CGGA, and CGGA (array) datasets." (PMID 35579998, 2022).
breast tumors (11 papers, 2009 to 2023). "A significant reduction in MCAM gene expression in breast tumour compared to normal tissue was confirmed using two datasets from GENT2, a compendium of microarray data processed to allow comparisons between studies." (PMID 37138793, 2023). "Although the sEMThigh population was largely represented by this single patient in the scRNA-seq dataset, 38 of the 1,093 breast tumours from the TCGA dataset were sEMThigh and this dataset showed a positive correlation between sEMT and MCAM gene expression." (PMID 37138793, 2023).
multiple sclerosis (11 papers, 2015 to 2025). A progressive autoimmune disorder affecting the central nervous system resulting in demyelination. "Increased expression of MCAM was shown in experimental autoimmune encephalomyelitis, a mouse model of multiple sclerosis." (PMID 41388158, 2025). "In an animal model of multiple sclerosis, an antibody targeting MCAM reduced Th17 cell infiltration into the CNS, thus ameliorating experimental autoimmune disease." (PMID 40332051, 2025). "Both studies strongly implicate MCAM+ T cells as key players in the pathogenesis of multiple sclerosis." (PMID 41388158, 2025). "There are several reports of MCAM+ T cells in multiple sclerosis and suggested their possible role in this inflammatory disease process." (PMID 34491483, 2021). "Melanoma cell adhesion molecule (MCAM) is a membrane-anchored glycoprotein expressed by a subset of T-cells and MCAM+ T-cells have been shown to contribute to neuroinflammation in multiple sclerosis." (PMID 33381120, 2020). "First, elevated levels of MCAM are typical for active inflammatory reactions, such as idiopathic myopathy, chronically inflamed tissues, inflammatory skin disease, rheumatoid arthritis, chronic obstructive pulmonary disease, or multiple sclerosis." (PMID 41388158, 2025). "Similarly, using anti-MCAM antibody, a significant decrease in infiltrated lymphocytes in the central nervous system (CNS) and decreased neuroinflammation in a mouse multiple sclerosis model was observed." (PMID 41388158, 2025). "ST14 was identified as an immune ligand for MCAM, which was enriched in CD4+ T lymphocytes that cross the BBB in multiple sclerosis lesions." (PMID 41388158, 2025). "Therefore, targeting MCAM may offer a therapeutic approach to multiple sclerosis therapy." (PMID 41388158, 2025).
autoimmune disease (10 papers, 2012 to 2022). A disorder resulting from loss of function or tissue destruction of an organ or multiple organs, arising from humoral or cellular immune responses of the individual to their own tissue constituents. "As such, modulation of the interaction between MCAM and laminin 411 represents a novel and selective approach that may help to maintain or restore homeostasis to inflamed tissues in autoimmune diseases." (PMID 22792325, 2012).
metastatic tumors (9 papers, 2012 to 2024). "iv) Melanoma cell adhesion molecule (MCAM): Expressed in 80% of metastatic tumors, MCAM is a cell adhesion marker." (PMID 38410760, 2024). "For example, both MCAM and THY1, which encode cell adhesion molecules of the immunoglobulin superfamily (IgSF-CAMs), are frequently overexpressed in metastatic tumor tissues." (PMID 30102725, 2018). "In particular, the promoters for the adhesion molecule MCAM/MUC18, which is overexpressed in tumors, and tyrosinase kinase receptor, c-KIT (silenced in 70% of metastatic tumors), have AP2α binding sites." (PMID 23634303, 2013).
pancreatic cancer (9 papers, 2012 to 2025). "In 2003, by using another anti-MCAM mAb, AA98, inhibition and reduction of blood vessel density in xenografted mice injected with human hepatocarcinoma, leiomyosarcoma, and pancreatic cancer were achieved." (PMID 41388158, 2025).
sarcoma (8 papers, 2015 to 2025). A usually aggressive malignant neoplasm of the soft tissue or bone. "Together, our studies reveal an important role for the KDM3A/Ets1/MCAM axis in pediatric sarcomas of distinct cellular and molecular ontogeny, and identify new targetable vulnerabilities in RMS." (PMID 32577157, 2020).
lung adenocarcinoma (7 papers, 2013 to 2025). A carcinoma that arises from the lung and is characterized by the presence of malignant glandular epithelial cells. "First, a significant difference in the expression level of MCAM was observed between sensitive and resistant lung adenocarcinoma cells." (PMID 40713600, 2025). "We found that MCAM expression was increased in EGFR-TKI-resistant lung adenocarcinoma and was involved in the process of EGFR-TKI resistance." (PMID 40713600, 2025). "Therefore, this study explored the expression and function of MCAM in EGFR-mutant the lung adenocarcinoma and the specific mechanism of EGFR-TKI resistance." (PMID 40713600, 2025). "Ectopic MCAM expression in HCC827 cells was examined after treatment with the IC50 of gefitinib or osimertinib to further clarify whether MCAM is involved in the acquired resistance of lung adenocarcinoma cells." (PMID 40713600, 2025). "The results obtained in the present study showed that KIF14 might regulate cell migration and adhesion through associations with CDH11 and MCAM; this increase in the membrane localization of CDH11 in lung adenocarcinoma cell lines is a novel finding with regard to the function of KIF14." (PMID 23626713, 2013). "Melanoma cell adhesion molecule (MCAM), a highly glycosylated type I transmembrane protein belonging to the immunoglobulin superfamily, is upregulated in EGFR-TKI-resistant EGFR-mutant lung adenocarcinoma." (PMID 40713600, 2025). "However, to the best of our knowledge, no studies have demonstrated that MCAM may regulate the resistance of lung adenocarcinoma to EGFR-TKIs through the JAK3 signaling pathway." (PMID 40713600, 2025).
mesothelioma (7 papers, 2016 to 2024). A usually malignant and aggressive neoplasm of the mesothelium which is often associated with exposure to asbestos. "In addition, survival analyses demonstrated that higher MCAM expression was significantly associated with worse prognosis in patients with brain low‐grade glioma (HR = 2.2, adjusted p‐value <0.05) and mesothelioma (HR = 2.8, adjusted p‐value <0.05) compared to other patients." (PMID 34961985, 2022).
rheumatoid arthritis (7 papers, 2007 to 2025). A chronic, systemic autoimmune disorder characterized by inflammation in the synovial membranes and articular surfaces. "Immunohistochemistry showed that MCAM is expressed almost exclusively in vascular ECs in synovial tissue from normal and rheumatoid arthritis patients." (PMID 41388158, 2025).
triple-negative breast carcinoma (7 papers, 2012 to 2025). An invasive breast carcinoma which is negative for expression of estrogen receptor (ER), progesterone receptor (PR), and human epidermal growth factor receptor 2 (HER2). "MCAM and Integrin β1 form a complex leading to radio resistance in triple-negative breast cancer." (PMID 40713600, 2025).
endometrial cancer (6 papers, 2009 to 2025). Primary or metastatic malignant neoplasm involving the endometrium (mucous membrane that lines the endometrial cavity). "In endometrial cancer, a spatially separated vascular CAFs subgroup characterized by high levels of MYH11, ESAM, MCAM, and EPAS1 was a poor prognostic factor for patients with endometrial cancer." (PMID 39764562, 2025).
liver cancer (6 papers, 2014 to 2025). An epithelial or non-epithelial malignant neoplasm that arises from the liver. "Identifying such proteins might provide new ways to treat YAP-associated liver cancer and highlight potential biomarkers to increase the sensitivity of AFP, CD166 and MCAM to diagnose liver cancer." (PMID 31501420, 2019). "We found that the true positive rate of liver cancer can be increased by the combined usage of previously discovered CD166 and MCAM, current identified CCT3 and traditional AFP." (PMID 31501420, 2019). "It is also worth noting that 15.4–30.6% of patients with liver cancer cannot be well diagnosed even when CD166, MCAM, CCT3 and AFP were combined used, this led us to discover more useful biomarkers to overcome this problem." (PMID 31501420, 2019).
Obesity (6 papers, 2021 to 2023). Accumulation of substantial excess body fat. "MCAM is the laminin alpha 4 receptor that was related to obesity, adipose tissue expansion, and weight gain." (PMID 36282842, 2022).
renal cell carcinoma (6 papers, 2016 to 2025). "Clinical studies in patients with diabetic nephropathy, IgA nephropathy, renal cell carcinoma, kidney transplants, and chronic kidney disease show correlations between MCAM expression (both tissue and soluble MCAM fractions) and disease severity, progression, and mortality." (PMID 41388158, 2025). "Interestingly, the α4 chain and its receptor Melanoma Cell Adhesion Molecule (MCAM) are highly expressed in the blood vessels of renal cell carcinomas and the levels of expression may serve to predict the patients’ outcome." (PMID 27809279, 2016). "One study has found that melanoma cell adhesion molecule (MCAM) and its extracellular matrix interaction partner laminin alpha 4 (LAMA4), which have emerged as the genes most consistently expressed in blood vessels, can predict poor survival in renal cell carcinoma." (PMID 28029655, 2017).
asthma (5 papers, 2015 to 2024). "MCAM is also strongly and transiently up-regulated in tracheal epithelium during repair, is required for tracheal epithelial regeneration, and is up-regulated in the bronchial epithelium of patients with COPD and asthma." (PMID 25944280, 2015).
cervical cancer (4 papers, 2013 to 2025). A primary or metastatic malignant neoplasm involving the cervix. "High lnc-FANCI-2 and low MCAM levels in cervical cancer tissues were found to be associated with patients’ survival." (PMID 40878909, 2025). "Consistently, lnc-FANCI-2 and MCAM levels are negatively correlated in cervical cancer patients, and low levels of MCAM and high levels of lnc-FANCI-2 indicate better prognosis." (PMID 40878909, 2025). "The significance of an inverse correlation of lnc-FANCI-2 and MCAM in CaSki cells was further investigated by analyzing their expression in 304 cervical cancer samples from the TCGA dataset." (PMID 40878909, 2025). "The opposite effects of lnc-FANCI-2 and MCAM on cervical cancer survival show that the cervical cancer patients with a higher level of lnc-FANCI-2 but a lower level of MCAM in the cervical tissue exhibited a better survival prognosis." (PMID 40878909, 2025). "High levels of lnc-FANCI-2 and low levels of MCAM expression in cervical cancer patients correlate with improved survival, indicating that lnc-FANCI-2 plays a critical role in regulating RAS signaling to affect cervical cancer progression and patient outcomes." (PMID 40878909, 2025).